YY1 (YY1 transcription factor)
Diseases named in the same sentence as YY1 in open-access papers (continued):
Sharing a sentence is not in itself a finding about the gene and the disease.
autoimmune uveitis (8 papers, 2024 to 2025). An autoimmune form of uveitis (disease). "From a mechanistic perspective, YY1 lactylation was found to promote microglial dysfunction in autoimmune uveitis, with this effect being mediated by the upregulation of inflammatory cytokine secretion and the promotion of cell migration and proliferation." (PMID 40672754, 2025). "Lactylation of Yin-Yang 1 (YY1) promotes microglial cell activation and inflammation in autoimmune uveitis." (PMID 40161494, 2025). "Corroborating these findings, another study on experimental autoimmune uveitis (EAU) revealed enhanced lactate modification of Yin Yang-1 (YY1) in retinal microglia." (PMID 40082399, 2025). "Collectively, the results showed that YY1 lactylation promoted microglial dysfunction in autoimmune uveitis by upregulating inflammatory cytokine secretion and boosting cell migration and proliferation." (PMID 38493498, 2024). "This study reveals that YY1 lactylation promotes microglial functions in autoimmune uveitis by upregulating inflammatory cytokine secretion and boosting cell migration and proliferation." (PMID 38493498, 2024). "YY1 lactylation intensifies autoimmune uveitis by facilitating the transcription of inflammatory mediators that influence microglial activity, thereby worsening the condition." (PMID 39325940, 2024). "Here, an increased YY1 lactylation in retinal microglia within in the experimental autoimmune uveitis (EAU) group is observed." (PMID 38493498, 2024). "Moreover, YY1 lactylation aggravated autoimmune uveitis by enhancing microglial functions via inflammatory genes and targeting the lactate/p300/YY1 lactylation/inflammatory genes axis may serve as a promising therapeutic strategy." (PMID 39611043, 2024).
B-cell lymphoma (7 papers, 2010 to 2024). "A subsequent study further confirmed that the NF-κB/YY1/Snail/Bcl-xL loop is associated with drug resistance in B-cell non-Hodgkin lymphoma (B-NHL) cells." (PMID 37686541, 2023). "Therefore, both YY1 and survivin serve a pro-tumorigenic role in aggressive B-NHLs, particularly in B-cell lymphomas (BLs), and survivin is likely a good potential diagnostic and prognostic biomarker for chemotherapy responses in patients with NHL." (PMID 37686541, 2023). "Once again, the analysis showed that among the mature aggressive B-cell lymphomas, BLs, BLs-like were the tumor subtypes with a significantly higher expression of both YY1 and BIRC5." (PMID 32899428, 2020). "Furthermore, aberrant YY1 expression has been associated with survival in some entities of B cell non-Hodgkin lymphoma (B-NHL), suggesting that YY1 could be a valuable biomarker in B-NHL." (PMID 29564133, 2018). "Finally, both YY1 and survivin may be additionally analyzed in the future as pharmacological targets in the search for new therapeutic approaches for the effective cure of resistant/relapsing B-cells lymphomas." (PMID 32899428, 2020). "Strikingly, the analyses of mixed B-NHL datasets evidenced that both YY1 and BIRC5 were significantly and highly overexpressed in BLs and high-grade B-NHLs, compared to their expression in other milder forms of B-cells lymphomas." (PMID 32899428, 2020).
Burkitt lymphoma (7 papers, 2014 to 2024). A rare form of malignant mature B-cell non-Hodgkin lymphoma. "Further validation experiments performed in Raji Burkitt’s lymphomas cells, demonstrated that YY1 silencing was associated with survivin downregulation and sensitized the cells to apoptosis." (PMID 32899428, 2020). "In Burkitt lymphoma, YY1 binds to this HS3 enhancer and recruits CBP to this region, which increases the histone acetylation of the c-Myc promoter and activates c-Myc gene expression." (PMID 24674326, 2014). "The expression of YY1 was inversely correlated with miR-200a in Burkitt′s lymphoma (BL) tissue." (PMID 35682560, 2022). "The two microRNAs were related to the expression of YY1 and downregulated in Burkitt's lymphoma." (PMID 31976313, 2020). "In an in vitro model using a cell line derived from Burkitt lymphoma (Ramos), we showed high expression of KLF4 and YY1, and the KLF4 promoter contained two consensus sites for YY1 binding." (PMID 31040909, 2019).
medulloblastoma (7 papers, 2021 to 2024). A malignant, invasive embryonal neoplasm arising from the cerebellum. "Other players implicated in the tumorigenic actions of HOTAIR in medulloblastoma pathogenesis include miR-1 and miR-206, both of which are its sponging targets, and have the capacity to modulate expression of zinc finger transcriptional repressor, Yin Yang 1 (YY1)." (PMID 38366205, 2024). "HOTAIR knockdown improves apoptosis rate, decreases the cell viability, clonogenicity, migration, and invasion, and reduces tumor volume in animal models; this oncogenic effect is medicated via the HOTAIR/miR-1-3p and miR-206/ YY1 axes in medulloblastoma." (PMID 39010056, 2024). "Enforced expression of HOTAIR significantly accelerates tumor progression and development in medulloblastoma through targeting miR-1 and miR-206 and inducing Yin Yang 1 (YY1) transcription factor." (PMID 38204968, 2023). "Indeed, elevated levels of HOTAIR and YY1 have been observed in tissues from clinical cases of human medulloblastoma, and in Daoy, D283 Med and D341 cell lines." (PMID 38366205, 2024). "Medulloblastoma tissues are observed to have elevated levels of LncRNA HOTAIR which binds to miR-1 and miR-206 and inhibits them to upregulate YY1." (PMID 35111757, 2021). "In medulloblastoma cells, HOTAIR is able to negatively regulate miR-1 and miR-206 expression which can directly target YY1, a transcription factor described as a metastasis inducer." (PMID 34576322, 2021).
oral cancer (7 papers, 2019 to 2025). "Noteworthy, YY1 protein expression is associated with enhanced proliferation and migration in oral cancer cells." (PMID 33315124, 2021). "YY1 in association with CARM1 promotes oral cancer carcinogenesis." (PMID 33344262, 2020). "Impressively, a novel study has mentioned that YY1 expression is raised in oral cancer, facilitating proliferation, angiogenesis and metastasis of oral cancer cells." (PMID 35778739, 2022). "Another miR-30c-5p target, Yin Yang 1 (YY1), is also overexpressed in oral cancer patient samples compared to adjacent normal tissue." (PMID 34572265, 2021). "Both in vitro and in vivo experiments revealed pro-proliferative, pro-angiogenic, and pro-metastatic roles of YY1 in oral cancer." (PMID 34572265, 2021). "YY1 also showed augmented expression in clinical tissue samples of oral cancer patients compared to adjacent normal tissues; its upregulation demonstrated pro-proliferative and pro-metastatic roles in oral cancer." (PMID 34497757, 2021). "AW8507 cells showed reduced proliferation when YY1 expression was silenced, indicating a pro-proliferative role of YY1 in oral cancer." (PMID 31217904, 2019). "The results of xenograft studies further corroborate the in vitro cellular data, emphasizing on the important role of YY1 in oral cancer growth." (PMID 31217904, 2019). "On the other hand, inducible silencing of YY1 resulted in reduced proliferation, reduced clonal propagation as well as slower migration of oral cancer cells." (PMID 31217904, 2019). "In clonogenic assay AW8507 cells formed fewer and smaller colonies under YY1 silencing conditions, indicating a necessity of YY1 for clonal propagation of oral cancer cells." (PMID 31217904, 2019). "Taken together, CARM1 and YY1 were found to regulate each other in a positive feedback loop to facilitate oral cancer progression." (PMID 31217904, 2019). "In this context, YY1 showed concomitant overexpression in oral cancer patient samples compared to adjacent normal tissue." (PMID 31217904, 2019). "In the present study investigation with silencing of both CARM1 and YY1 unraveled the oncogenic functions of both the proteins towards oral cancer manifestation." (PMID 31217904, 2019). "In order to understand the functional significance of YY1 overexpression in oral cancer, different tumorigenic assays were performed in AW8507_Tet-ON-shYY1 stable cell line with inducible silencing of YY1 expression." (PMID 31217904, 2019). "We wanted to investigate and determine the gene signature influenced by YY1 to contribute to oral cancer progression." (PMID 31217904, 2019). "Cell line based experiments as well as xenograft study revealed pro-neoplastic functions of YY1 in oral cancer." (PMID 31217904, 2019). "The inducible knock-down of YY1 in AW8507_Tet-ON-shYY1 cells with Doxycycline treatment was found to lead to reduction in expression of CARM1, indicating transcriptional regulation by YY1 in the context of oral cancer." (PMID 31217904, 2019). "Transcriptomics analysis as well as qRT-PCR validation clearly indicated pro-proliferative, pro-angiogenic and pro-metastatic role of YY1 in oral cancer." (PMID 31217904, 2019). "H-scoring with 27 pairs of oral cancer patient samples revealed significant upregulation of YY1 in oral cancer tumor tissue compared to adjacent normal tissue." (PMID 31217904, 2019). "Transcriptomic analysis with knock down of CARM1 in the context of oral cancer would be necessary to identify the genes which are regulated by both YY1 and CARM1." (PMID 31217904, 2019). "Therefore, a positive feedback loop is formed between CARM1 and YY1, mutually regulating each other, thereby driving the progression of oral cancer." (PMID 39964832, 2025). "In this study we demonstrate overexpression status of YY1 with oncogenic functions in oral cancer." (PMID 31217904, 2019).
oral cancer (continued). "We also identify YY1 to be a positive regulator of CARM1 gene promoter, where silencing of YY1 in oral cancer cell line could lead to reduction in expression of CARM1." (PMID 31217904, 2019). "Similarly, expression of genes involved in EMT as well as metastasis such as VIM, TWIST and MMP7 were reduced upon silencing of YY1 in qRT-PCR experiment, indicating a regulatory role of YY1 in metastasis and invasion of oral cancer." (PMID 31217904, 2019). "Therefore, microarray based transcriptomic analysis was performed to identify the genes directly or indirectly influenced by YY1 in oral cancer." (PMID 31217904, 2019). "The study also revealed that YY1 acts as a positive regulator of the CARM1 gene promoter, and silencing YY1 in oral cancer cells significantly reduces CARM1 expression." (PMID 39964832, 2025). "We also observed a positive correlation in protein expression of both YY1 and CARM1 in oral cancer tumor tissues." (PMID 31217904, 2019). "Taken together, these data prove that YY1 positively regulates CARM1 expression and is at least partly responsible for the overexpression of CARM1 in oral cancer patient tumors." (PMID 31217904, 2019). "The genome wide transcription factor enrichment profile from ENCODE repository revealed a few prospective TF candidates for regulation of CARM1 expression in oral cancer such as E2F4, CTCF, YY1 and cMyc etc.." (PMID 31217904, 2019). "Clinically relevant RNAi therapy and small molecule inhibitors could also be developed and employed targeting YY1 and CARM1 to suppress oral cancer growth in near future." (PMID 31217904, 2019). "As our results clearly suggest that YY1 positively regulates CARM1 promoter and CARM1 is highly overexpressed in oral cancer patient samples, we wanted to find out whether CARM1 overexpression is caused by upregulation of YY1 in the context of oral cancer." (PMID 31217904, 2019). "Furthermore, we performed mRNA expression analysis with knock-down of YY1 in a grade III, oral cancer cell line, AW8507." (PMID 31217904, 2019).
thyroid cancer (7 papers, 2019 to 2025). "Additionally, a single-nucleotide mutation in chromosome 4q32 (4q32A > C) is extremely rare, but this mutation attenuates SE activity and prohibits binding of POU2F1 and Yin-Yang 1 (YY1), which downregulates seRNA and enhances the predisposition of thyroid carcinoma (ATC)." (PMID 32278350, 2020). "For instance, a significant increase of YY1 expression was upregulated in both thyroid cancer cells and tissues." (PMID 34497757, 2021). "Further studies on the role of YY1 in thyroid cancer are needed to gain mechanistic understanding of how YY1 promotes thyroid tumorigenesis." (PMID 31824839, 2019). "Notably, YY1 was downregulated only in thyroid carcinoma, suggesting a potential tissue-specific regulation or tumor suppressor role in this context." (PMID 41009346, 2025). "The overexpression of YY1 in differentiated thyroid cancers has also been noted." (PMID 32093341, 2020). "Compared to other cancers, YY1 role in thyroid cancer has not been well-explored." (PMID 31824839, 2019).
acute lymphoblastic leukemia (6 papers, 2012 to 2025). Leukemia with an acute onset, characterized by the presence of lymphoblasts in the bone marrow and the peripheral blood. "Moreover, YY1 was found to positively regulate the expression of multi-drug resistance protein Gp-170, strongly linked to chemotherapy resistance in acute lymphoblastic leukemia." (PMID 39063014, 2024). "The clinical implications of HIF-1α in the regulation of YY1 were investigated by evaluation of expression of HIF-1α and YY1 in 108 peripheral blood samples and by RT-PCR in 46 bone marrow samples of patients with pediatric acute lymphoblastic leukemia (ALL)." (PMID 35163649, 2022). "Moreover, clinical studies show that YY1 correlates positively with P-gp expression in acute lymphoblastic leukemia (ALL), with high YY1 expression patients exhibiting significantly lower 5-year overall survival rates." (PMID 40867514, 2025). "We also tested two human pre-B acute lymphoblastic leukemia (ALL) lines (697 and JM-1) to determine whether they would also respond to elevated YY1 expression similar to murine B cell lines." (PMID 22292011, 2012).
Alzheimer disease (6 papers, 2010 to 2025). A progressive, neurodegenerative disease characterized by loss of function and death of nerve cells in several areas of the brain leading to loss of cognitive function such as memory and language. "YY1 plays important roles in neuroprotective pathways associated with ischemic damage, Parkinson’s and Alzheimer’s disease, and acts as a tumor suppressor or stimulator." (PMID 33923444, 2021). "FOXC1, GATA2 and YY1 were found as regulatory TFs in several neurological conditions, such as Alzheimer's disease and various others." (PMID 39153206, 2024). "Throughout life, YY1 regulates various neuroprotective pathways, playing a central role in ischemic damage, Parkinson’s and Alzheimer’s disease." (PMID 33102493, 2020). "A bioinformatics approach to uncover regulators of Alzheimer’s Disease appointed YY1 as one of the master regulators." (PMID 33102493, 2020). "YY1 expression can control iron-transferrin homeostasis in an age-dependent manner, regulate cell senescence and Alzheimer's disease-related amyloid processing." (PMID 21179406, 2010). "Astrocytic YY1 has proven to participate in the progression of other neurodegenerative pathologies like Alzheimer’s disease in which YY1 promotes the expression of the β-site amyloid precursor protein-cleaving enzyme 1 (BACE1), a prerequisite for β-amyloid peptides formation." (PMID 39904836, 2025). "Moreover, higher mRNA levels of YY1 were found in Alzheimer diseased brain and YY1 was defined as a “master regulator” in Alzheimer disease." (PMID 34115613, 2021). "Interestingly, in contrast to Parkinson’s, in Alzheimer disease higher levels of YY1 mRNA were detected in human autopsy-derived whole brain samples and isolated neuron samples compared to controls." (PMID 33102493, 2020).
cardiac hypertrophy (6 papers, 2020 to 2025). "Therefore, in this study, we postulated that YY1 would mediate DM-associated cardiac hypertrophy and subsequent HF." (PMID 39850120, 2025). "In addition, repression of HDAC5 phosphorylation and preventing HDAC5 nuclear export by YY1 overexpression significantly inhibited the increase in cell size and the re-expression of fetal genes associated with pathological cardiac hypertrophy." (PMID 37667300, 2023). "Hyperglycemia induced nuclear translocation of YY1, leading to Pim3 up-regulation, eventually developing into cardiac hypertrophy and HF." (PMID 39850120, 2025). "The same research group showed that overexpression of YY1 in a transgenic mouse model induced pathologic cardiac hypertrophy." (PMID 39850120, 2025). "Taken together, these data indicate that YY1 is involved in hyperglycemia-induced cardiac hypertrophy and HF." (PMID 39850120, 2025). "Pim3 or YY1 knockdown profoundly reduced cell size and inhibited the mRNA and protein expression of cardiac hypertrophy markers, as well as markedly attenuating myocardial hypertrophy and cardiac dysfunction." (PMID 39850120, 2025). "Under hyperglycemic conditions, sustained YY1 nuclear translocation induced significant Pim3 up-regulation, eventually leading to cardiac hypertrophy and HF in mice." (PMID 39850120, 2025). "Together, these findings indicate that YY1 acts as an upstream regulator to activate Mettl1 expression during cardiac hypertrophy." (PMID 38810124, 2024). "These regulators are transcription factors that are known from pathological cardiac hypertrophy, e.g., YY1, and fibrosis, e.g., SMAD binding motifs." (PMID 34065419, 2021). "In this study, we demonstrated that hyperglycemia-induced sustained YY1 nuclear translocation strengthened the binding of YY1 to the Pim3 promoter and markedly enhanced Pim3 promoter transcription activity, leading to Pim3 up-regulation, eventually contributing to cardiac hypertrophy and HF." (PMID 39850120, 2025). "We speculate that YY1-Pim3 signaling may play a crucial role in DM-induced cardiac hypertrophy and HF." (PMID 39850120, 2025). "Targeting YY1-Pim3 signaling may be a promising therapeutic avenue for DM-induced cardiac hypertrophy and HF." (PMID 39850120, 2025). "A previous study showed that YY1 was significantly up-regulated in cardiac hypertrophy and HF." (PMID 39850120, 2025). "YY1 acts as a transcriptional factor for Mettl1 during cardiac hypertrophy." (PMID 38810124, 2024). "Indeed, as we expected, YY1 was involved in hyperglycemia-induced Pim3 up-regulation in cardiomyocytes by binding to the Pim3 promoter and markedly enhancing Pim3 promoter transcription activity, eventually contributing to cardiac hypertrophy and HF." (PMID 39850120, 2025). "YY1 could prevent cardiac hypertrophy and suppresses dilated cardiomyopathy and cardiac fibrosis." (PMID 34054926, 2021).
Insulin resistance (6 papers, 2012 to 2025). Increased resistance towards insulin, that is, diminished effectiveness of insulin in reducing blood glucose levels. "The upregulation of YY1 during aging might compensate for both mitochondrial dysfunction and insulin resistance." (PMID 36880159, 2023). "Moreover, YY1 promotes the hepatosteatosis and insulin resistance, mainly via FXR, in the animal model." (PMID 30285651, 2018).
clear cell renal cell carcinoma (5 papers, 2020 to 2023). "In clear cell renal cell carcinoma, the YY1/HDAC2 complex reduces the expression of YTHDC1, which modulates the sensitivity of ccRCC to sunitinib by targeting the ANXA1-MAPK pathway." (PMID 37495623, 2023).
esophageal cancer (5 papers, 2021 to 2025). A primary or metastatic malignant neoplasm involving the esophagus. "Next, we performed an in silico analysis and, by doing so, found that YY1 and MGP expression exhibited a significant inverse correlation in the bladder and esophageal cancers." (PMID 39684309, 2024).